DRD3 (dopamine receptor D3)
Diseases named in the same sentence as DRD3 in open-access papers (continued):
Sharing a sentence is not in itself a finding about the gene and the disease.
depression (22 papers, 2013 to 2026). "It has been widely reported that the Gly carriers are more common and anhedonic than Ser/Ser carriers among patients with major depressive disorder, indicating that DRD3 Ser9Gly polymorphism is implicated in the pathogenesis of depression." (PMID 31143436, 2019). "Logistic regressions on the associations of the DRD3 variant rs2399496 with DSM-IV major depressive disorder (MDD) among sub-groups based on DSM-IV nicotine dependence (ND) statusa." (PMID 24927283, 2014). "Polymorphisms of the DRD3 gene also have been implicated in increasing the risk for major depressive disorder (MDD)." (PMID 23365649, 2013). "Interestingly, the same polymorphism has also been linked with depression severity in PD, indicating that in DRD3 Ser9Gly patients with Ser/Gly and Gly/Gly genotypes more care should be given to adjusting therapy and caring for non-motor complications." (PMID 34281267, 2021). "Indeed, studies reported that activation of astrocytic Drd3 signaling may account for the anti-depressive function of PPX in PD-associated depression, which is also linked to neuroinflammatory responses." (PMID 35896696, 2023). "Therefore, the right medial frontal gyrus activation related to DRD3 Ser9Gly polymorphism could be a biomarker for the occurrence and the severity of depression in PD." (PMID 31143436, 2019). "Therefore, DRD3 Ser9Gly polymorphism might be associated to the severity of depression characterized by anhedonia in PD patients with the Ser/Gly or Gly/Gly genotypes." (PMID 31143436, 2019). "Both the expression and function of DRD3 were significantly down-regulated in mice experiencing stress or in a model of depression, which is consistent with our present findings." (PMID 41459113, 2026). "Studies have shown that altered expression and function of DRD3 in patients and animal models of depression correlate with the severity of depression or depressive-like behavior." (PMID 36059987, 2022). "The (DRD3) gene affects patients with major depressive disorder and their response to antidepressant treatment." (PMID 26131011, 2015). "Variations in peripheral and postmortem levels of DRD3 and dopamine transporter have also been observed, suggesting broad dysregulation of dopaminergic pathways in depressive disorders." (PMID 24826212, 2014). "This indicates that DRD3 is a potential target for the treatment of depression." (PMID 36059987, 2022). "However, Drd3 antagonism has been shown to reduce (pre-adolescent) stress-induced depression-like behavior in adult mice." (PMID 29163035, 2017). "To determine the role of dopamine D3 receptor in preadolescent stress-induced adult depression-related disorders, we subjected male and female drd3 null mice to the preadolescent restraint stress and social isolation protocol and assessed depression-related behaviors in adulthood." (PMID 26619275, 2015). "To date, single studies have identified specific DRD3 variants associating with FTND defined ND, heaviness of smoking index, and time to first cigarette in the morning, as well as treatment response and remission in depression patients." (PMID 24927283, 2014). "Logistic regressions on the associations of the DRD3 variant rs2399496 and nicotine dependence (ND) with major depressive disorder (MDD): Models combining the ND (no/yes) and rs2399496 (TT = 0, TA = 1, or AA = 2 minor alleles) status." (PMID 24927283, 2014). "However, little research has been done to address the regulation of DRD3 expression in depression." (PMID 41459113, 2026). "Moreover, DRD3 expression and function are down-regulated during stress and depression, and antidepressant therapy can reverse these changes, suggesting that enhanced DAergic neurotransmission mediated by DRD3 down-regulation is involved in the adaptive changes underlying antidepressant activity." (PMID 36059987, 2022).
depression (continued). "One limitation is that several other dopamine receptors (such as DRD2 and DRD3), as well as other GABAA receptor subunits (such as α2, α3, β1, and δ), are also obviously involved in the regulation of depression." (PMID 33863350, 2021). "Our results indicate that reduced DRD3 levels may play a role in depression in DLB, and DRD3 specific dopaminergic agents may be beneficial." (PMID 40113786, 2025).
Parkinson disease (22 papers, 2010 to 2025). A progressive degenerative disorder of the central nervous system characterized by loss of dopamine producing neurons in the substantia nigra and the presence of Lewy bodies in the substantia nigra and locus coeruleus. "According to these studies, the present results show that DRD3 deficiency dampens neuroinflammation, one of the main processes involved in the triggering neurodegeneration associated to Parkinson’s disease." (PMID 31810491, 2019). "Previous studies have shown a fundamental role of DRD3 signalling in neurodegeneration associated to Parkinson’s disease." (PMID 31810491, 2019). "There are studies suggesting that genetics may affect the susceptibility to ICDs in patients on cabergoline; for example, a study found that the prevalence of the DRD3 p.Ser9Gly (rs6280) CT genotype in Indian patients with Parkinsonism is a risk factor for developing ICDs." (PMID 38957818, 2024). "DRD2/DRD3 agonists are currently used in clinical neurology as symptomatic treatment for neurological conditions such as Parkinson’s disease and restless leg syndrome." (PMID 40358175, 2025). "Of note, DRD3-signalling in CD4+ T cells has been shown to promote inflammation in animal models of Parkinson’s disease and inflammatory bowel diseases." (PMID 34920747, 2021). "In vivo, Drd3 blockade is neuroprotective and reduces inflammation in models of Parkinson’s disease." (PMID 34070429, 2021). "In this regard, DRD3 expressed in CD4+ T cells has been described to play a relevant role favouring the development of Parkinson’s disease in mice intoxicated with MPTP." (PMID 31810491, 2019). "The dopamine receptor D3 (DRD3) is a DA receptor subtype thought to play an important role in cognition in both healthy individuals and those with neuropsychiatric disorders, such as Parkinson’s disease and Alzheimer’s disease." (PMID 33596936, 2021). "Association of DRD3 and GRIN2B with impulse control and related behaviors in Parkinson's disease." (PMID 21034472, 2010). "Conversely, low dopamine levels, through the stimulation of high-affinity DRs, including DRD3, DRD4 and DRD5, have been shown to promote inflammation in animal models of Parkinson’s disease, inflammatory bowel diseases, allergic asthma, and MS." (PMID 34920747, 2021). "Of note, in the healthy human substantia nigra, DRD1, DRD3, DRD4, and DRD5 did not exhibit an expression pattern opposite to that of the Parkinson's disease‐associated molecule SNCA." (PMID 41249856, 2025). "For this purpose, a DRD3 selective antagonist PG01037 was i.p. administered at 30 mg/kg, a drug that has been previously proven to cross the blood-brain barrier and a dose that exerts a therapeutic effect attenuating neurodegeneration in two different mouse models of Parkinson’s disease." (PMID 31810491, 2019).
psychosis (12 papers, 2015 to 2024). "In AD, psychotic symptoms and aggressive behavior have been associated with homozygosity for DRD1 B2, whereas DRD3 1/1 or 2/2 homozygotes AD patients were more likely to develop psychosis." (PMID 35741861, 2022). "According to the authors, DRD3 mRNA levels can be used as a diagnostic marker to differentiate patients with early psychosis from healthy controls." (PMID 27795960, 2016). "Furthermore, the DRD3 SNP rs6280 was shown to provide a higher binding affinity to dopamine but also a higher susceptibility to tardive dyskinesia in patients with psychosis." (PMID 28125015, 2017). "Another study also didn’t find any significant associations between DRD2, DRD3 or DRD4 gene polymorphisms and levodopa-related psychosis in PD Caucasian patients." (PMID 35741861, 2022). "Disturbed dopamine function is important for psychosis, and most antipsychotic treatments target DRD2-like dopamine receptors (DRD2, DRD3, DRD4)." (PMID 37031222, 2023). "Five genes, DRD2, DRD3, HTR2A, OPRD1 and HTR7, are found shared by psychosis network and antipsychotics network." (PMID 32273551, 2020).
Anxiety (11 papers, 2015 to 2026). Intense feelings of nervousness, tension, or panic often arise in response to interpersonal stresses. "In particular, Drd3, a dopamine receptor associated with treatment-resistant major depression in humans and anxiety- and depressive-like behaviours in a laboratory mouse knockout, is downregulated in the maternal brain in hybrid pregnancies." (PMID 31598302, 2019). "Motivated by altered Drd3 expression in maternal brains, we tested for evidence of higher anxiety in mothers of hybrids during late gestation." (PMID 31598302, 2019). "To determine the role of dopamine D3 receptor in preadolescent stress-induced adult anxiety-related disorders, we subjected male and female drd3 null mice to the preadolescent restraint stress and social isolation protocol and assessed anxiety-related behaviors in adulthood." (PMID 26619275, 2015). "Genetic manipulation of Drd3 in mice has not yielded reports of consistent effects on anxiety-like behavior." (PMID 29163035, 2017). "We also observed that non-stressed female drd3-EGFP mice exhibited greater number of center zone entries compared to non-stressed male drd3-EGFP mice, suggesting that female mice exhibit less anxiety-like behaviors in a novel environment." (PMID 26619275, 2015).
Cognitive impairment (9 papers, 2013 to 2024). Abnormal cognition is characterized by deficits in thinking, reasoning, or remembering. "A possible genetic contribution of dopamine D3 receptor (DRD3) to cognitive impairment in Parkinson’s disease (PD) has yet to be investigated." (PMID 38363619, 2024). "Methylation of the promoter of dopamine receptor genes (DRD2, DRD3, and DRD4) also alters dopamine expression and causes cognitive deficits associated with SCZ." (PMID 36406755, 2022). "In accordance with our results, it has been reported that DRD1, DRD2, DRD3, DRD4, and SLC2A9 are associated with cognitive performance or cognitive impairment." (PMID 34285142, 2021). "The genes of cognitive impairment modified by DNA methylation include GAD1, BDNF, DRD3, DRD4, and 5HTR1A." (PMID 36406755, 2022).
glioma (5 papers, 2015 to 2025). A benign or malignant brain and spinal cord tumor that arises from glial cells (astrocytes, oligodendrocytes, ependymal cells). "Expression of HERV-W env in human glioma cells results in a two- to fourfold increase in expression of brain-derived neurotrophic factor (BDNF), neurotrophic tyrosine kinase receptor type 2 (NTRK2), and dopamine receptor D3 (DRD3)." (PMID 26793126, 2015).
bipolar disorder (4 papers, 2015 to 2024). A disorder of the brain that causes unusual shifts in mood, energy, activity levels and the ability to carry out day-to-day tasks. "One example is a study that reported a significant interaction effect between BDNF Val66Met and DRD3 Ser9Gly genotypes, influencing bipolar disorder." (PMID 26091093, 2015). "Noteworthy findings include associations of DRD3 with IL6 and TP35 in chronic alcoholic intoxication, alongside implications of DIO1 (a selenium target), DIO2, and DRD3 in thyroid diseases and bipolar disorders, hinting at potential connections to pathways involving exercise and ROS." (PMID 39635461, 2024).
Dyskinesia (4 papers, 2015 to 2022). A movement disorder which consists of effects including diminished voluntary movements and the presence of involuntary movements. "Increased risk for developing L-dopa induced dyskinesia was seen in the Dopamine receptor 3 (DRD3) rs6280 polymorphism in a Korean population." (PMID 34281267, 2021). "The Ser9Gly mutation in the DRD3 dopamine receptor gene is associated with increased risk of dyskinesia in risperidone treated patients." (PMID 26937359, 2015). "Carriers of dopamine receptors DRD2 haplotypes and possibly the BDNF variants rs6265 and DRD3 haplotypes, were at increased risk of dyskinesia, suggesting that these genes may be involved in dyskinesia-related pathomechanisms." (PMID 35743271, 2022). "In another study, the carriers of dopamine receptor DRD2 and DRD3 haplotypes, as well as the BDNF variant rs6265, were associated with an increased risk of dyskinesia, suggesting that these genes may be implicated in dyskinesia-related pathomechanisms in Parkinson’s disease patients." (PMID 35743271, 2022).
mental disorder (4 papers, 2021 to 2023). A disease that has its basis in the disruption of mental process. "DRD2 rs1800497 and DRD3 rs6280 are involved in nicotine dependence in patients with treatment-resistant mental disorders." (PMID 35455685, 2022). "This is the first study that showed the involvement of DRD3 rs6280 in nicotine dependence in patients with mental disorders." (PMID 35455685, 2022).
alcoholism (3 papers, 2013 to 2023). "Rs2134655 on DRD3 identified to be associated with the alcoholism susceptibility is related to the signal transduction of cAMP and Rap1 pathways." (PMID 28512340, 2017). "On the basis of this general model, we identified rs2134655 on DRD3 with unequal probabilities of alcoholism susceptibility (p = 0.027)." (PMID 28512340, 2017). "In addition, smokers who carried the risky allele on GRIN2B tended to have an early alcoholism onset than those on DRD3 (rs2134655)." (PMID 28512340, 2017). "Thus, the mechanism underlying ALDH1A1-related alcoholism is different from the gene cluster of DRD2, DRD3, GRIN2B, and NTRK2, which is directly involved in behavioural rewarding effects of alcohol consumption." (PMID 28512340, 2017). "The cluster of DRD2 and GRIN2B share the alcoholism pathway with NTRK2 (rs1439047) and have the same pathways of neuroactive ligand–receptor interaction and dopaminergic synapse as does DRD3 (rs2134655)." (PMID 28512340, 2017). "We tested genetic association of three polymorphisms in the dopaminergic pathway genes namely rs4532 in DRD1, rs6280 in DRD3 and a 120 bp duplication in 1.2 kb upstream region of DRD4 with alcohol dependence among male subjects from the North India." (PMID 24135011, 2013).
Alzheimer disease (3 papers, 2006 to 2021). A progressive, neurodegenerative disease characterized by loss of function and death of nerve cells in several areas of the brain leading to loss of cognitive function such as memory and language. "Of note, astrocytic expression of DRD3 was significantly exacerbated in Alzheimer’s disease patients, a neurodegenerative disorder involving chronic neuroinflammation." (PMID 31810491, 2019).
breast carcinoma (3 papers, 2022 to 2024). "In the only studies in cancer, the expression of both DRD2 and DRD3 was found to be increased in breast cancer patients, and DRD2 and DRD3 were found to have the same expression levels in the cholangiocarcinoma cell lines Mz-chA-1 and SG231." (PMID 36456906, 2022). "Similarly, the dopaminergic system, highlighted in recent studies, indicates that dopamine receptors, particularly DRD2 and DRD3, are upregulated in breast cancer, potentially contributing to tumor growth and progression." (PMID 39123356, 2024). "The overexpression of DRD2 and DRD3, with concomitant silencing of DRD5 expression, confirms the presence of dopaminergic abnormalities in breast cancer patients." (PMID 38928253, 2024). "But we had found that DRD3 expression was lower in HCC tissues, which is in contradiction to Akbari’s findings in breast cancer." (PMID 36456906, 2022).
cocaine addiction (3 papers, 2012 to 2017). "Concerning the known dopamine receptors, it has been reported that DRD1 and DRD2 are the most involved in cocaine addiction, whereas DRD3 and DRD4 are less relevant in the addiction process." (PMID 23285158, 2012).
impulse control disorder (3 papers, 2019 to 2025). A category of behaviors that can be loosely defined as the failure to resist an impulsive act or behavior that may be harmful to self or others. "Recently, some studies reported that DRD3 Ser9Gly polymorphism was associated with impulse-control disorders in PD patients, but their results were inconsistent." (PMID 31143436, 2019). "Fourthly, our study did not include some essential clinical symptoms such as impulse-control disorders, aberrant decision-making, hallucinations, and behavioral addictions which might be associated with DRD3 Ser9Gly polymorphism in PD patients." (PMID 31143436, 2019).
migraine (3 papers, 2009 to 2017). "For instance, a functional variant (Ser9Gly) of the dopamine D3 receptor (DRD3), although not confirmed in other studies, is associated with risk and age-at-onset of ET, the frequencies of the functional variant were found to be similar between ET patients with and without migraine." (PMID 28288163, 2017). "Also reports in the literature exist that migraineurs have an increased density of dopamine receptors DRD3 and DRD4 on lymphocytes and that DA agonists can bring about migraine." (PMID 24403849, 2013).
mood disorder (3 papers, 2013 to 2023). A cognitive disorder a disturbance in which the person's mood is hypothesized to be the main underlying feature. "This study sought to explore the role of the DRD2 rs1800497 and DRD3 rs6280 polymorphisms in nicotine addiction among patients with treatment-resistant mood disorders and schizophrenia spectrum disorders." (PMID 35455685, 2022). "In summary, the present study demonstrates that the DRD3 ser9gly variant influences in vivo DA release in the context of unpredicted reward, a finding with potentially important implications for the pathophysiology and treatment of addiction and mood disorders." (PMID 23365649, 2013). "Currently, no studies aimed at examining the relationship between DRD2, DRD3, COMT, and OPRM1 polymorphisms, the 5-HTTLPR genotype, and smoking habit and nicotine addiction in patients with treatment-resistant mood disorders and schizophrenia-spectrum disorders." (PMID 35455685, 2022). "In the cluster, particular attention was given to investigating the risk posed by dopamine receptors genes (i.e., DRD1, DRD2, DRD3, and DRD4) in the development of mood disorders." (PMID 36833279, 2023).
neuroblastoma (3 papers, 2009 to 2019). Neuroblastoma (NB) is the most common solid, extracranial childhood tumor. "Although dopamine was reported to regulate AKT-mTOR signaling in human SH-SY5Y neuroblastoma cells, the exact role of dopamine on DRD3 is unclear due to the fact that other DRs are also highly expressed in the neuroblastoma cells." (PMID 29786666, 2018). "In neuroblastoma cells, the induction of DRD4 was much more pronounced (about eightfold compared to 48-hr untreated control levels) than that of DRD3." (PMID 19653907, 2009). "In conclusion, there seems to be an inverse correlation between DRD3/DRD4 and DRRF levels in the context of SK-NF-I neuroblastoma cells." (PMID 19653907, 2009).
opioid use disorder (3 papers, 2022 to 2024). A substance-related disorder that involves the recurring use of opioids despite negative consequences. "Frequency of the dopamine receptor D3 (DRD3) (rs6280) vs opioid receptor μ1 (rs1799971) polymorphic risk alleles in patients with opioid use disorder (OUD): A preponderance of dopaminergic mechanisms?" (PMID 38765881, 2024).
substance abuse (3 papers, 2012 to 2024). The use of a drug for a reason other than which it was intended or in a manner or in quantities other than directed. "The DRD3 gene has been reported to be associated with substance abuse and cocaine and heroin abuse but others have not reported association with abuse of either drug." (PMID 22963930, 2012). "There are five dopamine receptor genes, DRD1, DRD2, DRD3, DRD4, and DRD5, which are mainly related to different risky behaviors like substance abuse and addiction." (PMID 38254998, 2024).